AFF3 (ALF transcription elongation factor 3)
Diseases named in the same sentence as AFF3 in open-access papers (continued):
Sharing a sentence is not in itself a finding about the gene and the disease.
lentivirus infection (1 paper, 2023). Virus diseases caused by the Lentivirus genus. "Whole-mount analysis of regenerated hair follicles revealed the expression of mTagBFP2 protein in the hair bulb region including hair matrix and IRS or DPCs in the group with lentivirus infection into epithelial cells or dermal cells, suggesting the expression of Ptn and Aff3." (PMID 37542032, 2023).
opioid use disorder (1 paper, 2023). A substance-related disorder that involves the recurring use of opioids despite negative consequences. "We also detected associations near XKR6 and AFF3, which have been recently implicated in externalizing psychopathology, and PTPRF and KDM4A, recently implicated in problematic opioid use and opioid use disorder." (PMID 37173343, 2023).
cancer (12 papers, 2017 to 2024). A tumor composed of atypical neoplastic, often pleomorphic cells that invade other tissues. "For example, this was the case with CDK12, which is essential in ~ 30% of cancer cells, and AFF3 which is essential in just a few cells." (PMID 36577800, 2022). "As an oncogenic gene for β-catenin mediated tumorigenesis, AFF3 can act on transcription and RNA splicing in some aggressive cancer." (PMID 35874638, 2022). "With the recent interest and success of epigenetic therapies for cancer treatment, it is tempting to speculate that AFF3 may be a druggable protein and that its overexpression may help identify patients whose tumors have intrinsic resistance to tamoxifen and a high-risk phenotype." (PMID 30326937, 2018). "Together, these types of observations could be interpreted that in some proportion of cancer cell lines, CDK12 and AFF3 may have synergistic effects on cell proliferation and survival, potentially affording synthetic lethal opportunities." (PMID 36577800, 2022). "As a cancer-specific fragile site, it is possible that AFF3 is lost without any selective pressure for its preservation." (PMID 30326937, 2018).
tumor (10 papers, 2016 to 2024). "Some of the identified prognostic DE RBPs have been reported associated with tumor progression, such as RBM47, LUZP4, AFF3, PPARGC1A, PPARGC1B, PABPC3, and PNLDC1." (PMID 33224957, 2020). "In tumor tissues, seven gene amplification mutations included CDK4 (Mutation abundance, MA:1.57), AKT2 (MA:1.65), CCND2 (MA:1.63), MDM2 (MA:1.57), NTRK1 (MA:2.38), AXL (MA:1.65), and KRAS (MA:1.63), as well as the AFF3 gene missense (c.1781_1787del insC)." (PMID 37089080, 2023). "Several of the genes upregulated in CTNNB1-mutated tumours have previously been described as overexpressed in CTNNB1-mutated adrenal lesions, regardless of type of hormone production or differentiation level: AFF3, ISM1, NKD1, ENC1 and RALBP131,32." (PMID 31000732, 2019). "In contrast, somatic mutations in tumor-promoting genes (FGFR1, RAC1, AFF3, AFF4, TSC2) may be intuitively associated with unfavorable prognosis." (PMID 30662871, 2018). "Our results also presented that the AFF3 gene was more highly expressed in RC tumor cells than in normal cells (P < 0.001)." (PMID 38886730, 2024). "The correlation of AFF3 and DAAM2 with the candidate miRNAs was detected at all tumor locations." (PMID 37987361, 2023).
AFF3 also shares sentences with these, for which no sentence is quoted: prostate carcinoma (3 papers); colon cancer (2); neurodevelopmental disorder (2); type 1 diabetes- (2); adrenal tumours (1); arrhythmogenic right ventricular cardiomyopathy (1); cannabis dependence (1); cardiovascular disease (1); celiac disease (1); cholangiocarcinoma (1); colorectal cancer (1); cortical atrophy (1); COVID-19 (1); diabetic nephropathy (1); endometriosis (1); focal segmental glomerulosclerosis (1); gastric cancer (1); glioblastoma (1); Graves disease (1); Head–neck squamous cell carcinoma (1); Horseshoe kidney (1); Hypertension (1); immune diseases (1); insomnia (1); kidney (1); kidney failure (1); muscle disorders (1); Neurodevelopmental delay (1); neurological diseases (1); Nievergelt Syndrome (1).
A further 8 diseases each share a sentence with AFF3 in 1 paper.